IL6 (interleukin 6)
Diseases named in the same sentence as IL6 in open-access papers (continued):
Sharing a sentence is not in itself a finding about the gene and the disease.
brain injury (continued). "Elevations in peripheral levels of IL-6 and TNFα have been reported following blast exposure in military personnel, suggesting that mild brain injuries may have similar biomarker changes." (PMID 32508732, 2020). "A resampled ordinary least squares regression was used to evaluate the relationship between IL-6 concentrations and concussion status, while partial least squares regression was used to evaluate the relationship between IL-6 and both symptom burden and time to clinical recovery." (PMID 32343752, 2020). "Moreover, exosomes derived from exfoliated deciduous teeth stem cells have also been reported to inhibit IL-6 and TNFα production in LPS-stimulated BV-2 microglial cells and to dampen microglia activation in an animal model of traumatic brain injury." (PMID 30898154, 2019). "This suggests that IL-6 may have biphasic roles in the pathogenesis of hypoxic brain injury: it induces inflammation and injury early after the insult but then contributes to cytokine-mediated repair at later time points." (PMID 30089504, 2018). "Similarly, higher blood IL-6 intracranial gradients at the time of hospital admission were observed in brain trauma patients with fatal outcome in the 6 months following, compared with survivors." (PMID 30202571, 2017). "Previous experimental studies have shown that brain trauma initiates a cascade of multiple anti- and proinflammatory pathways with permeability-increasing properties, such as release of various cytokines such as IL6, TNF alpha, and IL10." (PMID 27822741, 2017). "Furthermore, they can secret proinflammatory cytokines such as TNF-α, IL-1β and IL-6 to recruit other immunocytes such as neutrophils and lymphocytes, which further aggravate brain injuries." (PMID 26086994, 2015). "Lack of anti-inflammatory response at P1 might deprive the challenged brain of neurotrophic factors - such as TGF-β1, IL-10, IL-1ra and IL-6 - involved in neuronal survival and brain tissue repair following brain injuries." (PMID 21599903, 2011). "However, it has been suggested that IL-6 might be released as a protective response after hypoxic-ischemic brain injury and is involved in the repair process in the sub-acute stage of HIE." (PMID 34282369, 2021). "IL-6 KO mice that suffer compromised inflammatory responses, increased oxidative stress, impaired neuroglial activation and decreased lymphocyte recruitment, show a slower rate of recovery and healing in several models of neuroinflammatory, degenerative and traumatic brain injury." (PMID 25026958, 2014). "In this regard, specific proinflammatory cytokines, including IL-1β, IL-6, TNF-α, and IFN-γ, and markers of brain injuries, such as NFL and GFAP, have been proposed as etiological factors of SB/SI development." (PMID 38338174, 2024). "Other work shows that pan-IL-6 inhibition reduced injury-induced serum IL-6, keratinocyte-derived chemokine, and MIP-1α levels 24 h after hypoxic brain injury in mice." (PMID 38840141, 2024). "This study, to our knowledge, is the first time to show that the increased expression of IL-1β, IL-6, and TNF-ɑ genes on days 3 and 7 after brain trauma can be inhibited remarkably by propofol administration." (PMID 39810851, 2024). "Elevated cytokines and other inflammatory mediators such as IL-1α, IL-6, and TNF-α were also confirmed in other studies of traumatic brain injury, in which the traumatic stress response was one of the causes." (PMID 39282512, 2023). "Recent studies suggested that IL-6 can stimulate the migration of cultured cortical neurons, and that TNF-α promotes neurogenesis and brain repair in response to brain injury and infection in cultured neural stem/progenitor cells." (PMID 35742844, 2022). "IL-6 and TNF-a are biomarkers of acute inflammation peaking within 24 h post sports-related concussion." (PMID 35631280, 2022). "Brain injury induces the activation of M1 microglia and releases proinflammatory cytokines, such as TNF-α, IL-1β, and IL-6." (PMID 32922507, 2020).
brain injury (continued). "For example, IL-6 as a pleiotropic and variably glycosylated cytokine and INF-γ as an immune-regulatory cytokine were reported to impact both PTB and neonatal brain injury." (PMID 32511256, 2020). "Within the injured spinal cord and after traumatic brain injury, TNF-α and IL-6 are the two major cytokines produced by peripheral immune cells and activated glia adding to detrimental neuroinflammation." (PMID 33144615, 2020). "Compared to the ~2-fold increase in IL-1β, there was a ~6-fold increase in IL-6 expression after TBI implying that this protein, among others, is more central to the inflammatory response in brain trauma." (PMID 27199506, 2016). "Gut barrier dysfunction and enhanced translation of NF-κB, TNF-a, IL-1b, IL-6, and ICAM-1 were observed in Nrf2−/− mice after traumatic brain injury." (PMID 27009867, 2016). "Together with IL-1β and IL-6, TNF-α is one of the major pro-inflammatory cytokines released by activated microglia following ischemic brain injury." (PMID 17150094, 2006). "Previous research has demonstrated increased serum levels of inflammatory cytokines, including interleukin 8, growth-related genes alpha, and interleukin 6 (IL-6) in patients with NPE following non-traumatic brain injury." (PMID 37432487, 2023). "Likewise, in an animal model of traumatic brain injury, the agonism of CB2R (GP1a) attenuated pro-inflammatory M1 macrophage polarization, increased anti-inflammatory M2 polarization, and reduced IL-6 expression." (PMID 36232883, 2022). "Furthermore, SHD promotes the level of IL-6 and APP proteins in rats after ischemic brain injury and reduces the level of AKT1 and VEGFA proteins." (PMID 35097126, 2022). "Yet, despite these limitations, the results of the current study were able to identify a robust correlation between IL-6 and the interaction between an acute concussion and a history of concussion, that was not influenced by sex or recent physical activity." (PMID 32343752, 2020). "Similarly, within clinical studies, increased levels of IL-6, TNF, IL-10, C-C motif chemokine ligand 2 (CCL2) and IL-8 peak within the first 2 days following brain injuries and then return to normal over several weeks." (PMID 33143727, 2020). "IL-6 is involved in the modulation of inflammatory activity following a TBI, with evidence pointing to the importance of the balance of pro- and anti-inflammatory levels in the promotion of recovery following TBIs and concussions." (PMID 32450801, 2020). "Sevoflurane pretreatment can activate TLR3 and TLR9 signaling pathway, upregulate TLR3 expression and TRIF expression, decrease TLR9 expression, and downregulate NF-κB expression and inhibited the production of S100β and IL-6, thereby lessening CPB inflammation-induced brain injury." (PMID 29445737, 2017). "In coherence with previous literature, in our study Il-6, IL-1ra, Il-8, IL-10, IL-15, MCP-1, MIP-1β, and IP10 were selected in the first two components of PCA as strong predictors of outcome confirming their role in the pathophysiology of brain injury." (PMID 27324502, 2016). "Inflammatory mediators, including IL-1β, IL-6, IL-10, TNF-α and NF-κB were assessed to examine whether GLGZD was involved in the inflammatory response in ischemic brain injury." (PMID 25815894, 2015). "Expression of the inflammatory marker genes COX-2, iNOS, and IL6 was not significantly different between the anesthetic protocols at 15 minutes and 24 hours after experimental brain trauma." (PMID 21625505, 2011). "The innovation of this study lies in the integration of inflammatory biomarkers (IL-6, CRP, NSE), providing mechanistic insights into neuroprotection and systemic inflammatory modulation, strengthening the study’s translational relevance for traumatic brain injury management." (PMID 40443507, 2025).
brain injury (continued). "Compilation of all the recorded IL-6 values for the ICP ≤ 20 mm Hg and ICP ≥ 25 mm Hg groups yielded a receiver operator characteristic curve with an area under the curve of 0.81, suggesting that IL-6 is a good prognostic marker for ICP in isolated brain injury." (PMID 20222971, 2010). "Regression analysis identified a negative relationship between plasma IL-6 concentrations and the interaction between an acute SRC and a history of concussion (β = -0.29, p = 0.029)." (PMID 32343752, 2020). "Plasma concentrations of TNF-α, IL-6 and CRP in subjects without injury or following control trauma and traumatic brain injury were determined." (PMID 23894384, 2013).
cerebral infarction (99 papers, 2010 to 2025). An ischemic condition of the brain, producing a persistent focal neurological deficit in the area of distribution of the cerebral arteries. "The increase of IL-6 is closely associated with the size of cerebral infarction and the degree of neurological impairment." (PMID 34504432, 2021). "Our results found that polymorphisms of IL-1α −899C/T and IL-18 −607C/A (under all the genetic models), and IL-6 −572C/G (under the allelic model, heterogeneity model and dominant model) were associated with increased the risk of cerebral infarction." (PMID 27679860, 2016). "In conclusions, our results suggested that polymorphisms of IL-1α −899C/T, IL-6 −572C/G and IL-18 −607C/A were positive correlated with increased the risk of cerebral infarction." (PMID 27679860, 2016). "Subgroup analysis by ethnicity showed that polymorphisms of IL-6 −174G/C and IL-10 −1082A/G were significantly associated with cerebral infarction risk in Asians." (PMID 27679860, 2016). "Our result showed that IL-1α −899C/T and IL-18 −607C/A (under all the genetic models), and IL-6 −572C/G (under the allelic model, heterogeneity model and dominant model) were associated with increased the risk of cerebral infarction (P<0.05)." (PMID 27679860, 2016). "IL-6 has been previously linked to small vessel disease and silent cerebral infarctions." (PMID 30828313, 2019). "In conclusion, IL-1α −899C/T, IL-6 −572C/G and IL-18 −607C/A might be risk factors for cerebral infarction development." (PMID 27679860, 2016). "In addition, the reduction of IL-6 induced by the combined extract of O. sativa and A. graveolens also leads to the increase in eNOS expression and the improvement of brain blood supply which in turn decreases brain infarction and neuronal loss." (PMID 31827714, 2019). "Subgroup analysis by ethnicity showed that IL-6 −174G/C polymorphism (under all the five models) and IL-10 −1082A/G polymorphism (under the allelic model and heterologous model) were significantly associated with increased the cerebral infarction risk in Asians." (PMID 27679860, 2016). "Studies indicate that puerarin treatment in tMCAO rats decreases cerebral infarction volume, enhances neural function, and lowers pro‐inflammatory factors IL‐1β, IL‐6, and TNF‐α, likely via CAP activation." (PMID 40715012, 2025). "In this study, we found that IL-6 and IL-2 were elevated in aSAH patients who presented with new cerebral infarcts on CT imaging at 1 week or 2 weeks post-injury when compared to patients who did not demonstrate this finding." (PMID 40427506, 2025). "M1 microglia (with TNF-α or CD86 as markers) generate pro-inflammatory factors, such as TNF-α, IL-1β, IL-6, and interferon-γ, which promote inflammation and exacerbate I/R injury and cerebral infarction." (PMID 39391701, 2024). "Ischemic-hypoxic stimulation in cerebral infarction prompts monocytes to produce inflammatory mediators like interleukin-1 (IL-1), IL-6, IL-8, and tumor necrosis factor (TNF), leading to excessive inflammation that worsens brain tissue damage." (PMID 39030494, 2024). "Combined with inflammatory factors CRP and IL-6, it has important clinical value in diagnosing the severity and prognosis of cerebral infarction and is expected to be a biomarker for diagnosing and predicting the progression and prognosis of ACI." (PMID 37119591, 2023). "Ischemic hypoxia changes after cerebral infarction (CI), in which many proinflammatory cytokine such as IL-1, IL-6 as well as cytokines such as TNF-α are significantly released in the body before the inflammatory cell cascade occurs." (PMID 37369997, 2023). "Meanwhile, the present study also compared the relationship between NF-κB p65, IL-6, and cerebral infarct volume, and the results also showed statistically significant but relatively low correlation coefficients." (PMID 36643631, 2023). "The correlation between S100A1, NF-κB p65, and IL-6 levels and cerebral infarction volume was detected by Pearson correlation analysis." (PMID 36643631, 2023).
cerebral infarction (continued). "Inflammatory factors TNF-α, IL-6, and IL-1β participate in the process of early inflammatory injury of cerebral infarction." (PMID 36936654, 2023). "Histopathological analysis and measurement of brain infarct size were performed, and cerebral levels of IL-6, IL-10, TNF-α, ICAM-1, NF-κB p65, and total antioxidant capacity were assessed." (PMID 38313176, 2023). "The potential medicinal ingredients of ZTC mainly act on core targets such as ALB, AKT1, and IL-6, and then regulate related molecular pathways to achieve the effect of treating or delaying cerebral infarction." (PMID 35047043, 2022). "Another study on cerebral infarction also revealed lowered serum levels of IL-6 and TNF-α following rTMS treatment." (PMID 35392634, 2022). "Our results suggested that both pretreatment with DEX and AG490decreased the Longa score and cerebral infarct areas following cerebral I/R.After treatment with IL-6, the effects of DEX on abrogating these pathologicalchanges were reduced." (PMID 35858000, 2022). "Compared with the DEX group, cerebral infarction area was significantlyincreased in the DEX+IL-6 group (16.32±3.39%)." (PMID 35858000, 2022). "Cross-sectional studies have found that TNF-α, IL-1, IL-6 and CRP are associated with WMH, silent brain infarcts, lower eGFR levels and a higher UACR." (PMID 34072230, 2021). "The introduction of the Jak2 inhibitor AG490 blocked IL-6/Jak2 signaling, resulting in the amelioration of the poststroke neurological deficit, brain infarction, brain edema, oxidative stress, pro-inflammatory cytokine expression, and caspase-3 activation." (PMID 34943061, 2021). "Plasma D-lactate, zonulin, LPS, TNF-α, IFN-γ, and IL-6 were significantly increased after cerebral infarction (P < 0.05)." (PMID 31316450, 2019). "In this same study, the author confirmed that plasma irisin levels were negatively associated with brain infarct volume, the neurological deficit score, and plasma TNF-α and plasma IL-6 concentrations." (PMID 29720216, 2018). "Thus, this study shines light onto IL-6 and IL-2 as potential targets contributing to the pathophysiology of aSAH complicated with cerebral infarct." (PMID 40427506, 2025). "In addition to conventional vascular risk factors, serum biomarkers such as interleukin-6 (IL-6) and C-reactive protein (CRP) have been studied about silent brain infarction (SCI), reflecting systemic inflammation." (PMID 40917659, 2025). "Plasma S100A1, NF-κB P65, and IL-6 significantly differed from cerebral infarction volume." (PMID 36643631, 2023). "In addition to brain infarct volume and histopathological assessment, the brain tissues were harvested to evaluate cerebral IL-6, IL-10, TNF-α, ICAM-1, NF-κB p65, and total antioxidant capacity levels." (PMID 36567842, 2022). "The relationship between IL-6 gene polymorphism and increased risk of cerebral infarction has been suggested, although this was not confirmed by the other published results and further studies of this issue are required." (PMID 31701356, 2020). "A delayed increase in IL-6 is observed in aSAH patients with cerebral infarction." (PMID 33329313, 2020). "Thus, the possibility of finding a silent brain infarction increases significantly by measurement of PC-Acro, IL-6 and CRP in plasma together with 3-HPMA in urine, and contributes to maintenance of quality of life (QOL) of the elderly." (PMID 32824278, 2020). "Additionally, the increases in plasma LPS, TNF-α, IFN-γ, and IL-6 after cerebral infarction coincided with overgrowth of the Bacteroidetes phylum (P < 0.001)." (PMID 31316450, 2019). "Intriguingly, we found a delayed increase in serum IL-6 in patients developing cerebral infarction." (PMID 29194369, 2017). "After MDSC depletion, the anti-inflammatory and neuroprotective effects of CGRP in cerebral infarction mice were markedly attenuated, as evidenced by increased expression of TNF-α, IL-1β and IL-6 and elevated neuronal apoptosis." (PMID 40963921, 2025).